TP63 (tumor protein p63)
Diseases named in the same sentence as TP63 in open-access papers (continued):
Sharing a sentence is not in itself a finding about the gene and the disease.
breast cancer (continued). "Lineage associated transcription factors include MITF for the melanoma cell line SK-MEL-5, TP63 for the lung cancer line A549, KLF5 for the colon cancer line HT-29, and ETS family transcription factors for prostate, colon, ovarian, and breast cancer cell lines." (PMID 28854983, 2017). "Importantly, targeted depletion of IL13Rα2 resulted in dramatic suppression of lung metastasis formation in vivo that is likely to be attributed, at least in part, to STAT6-dependent induction of tumor protein 63 (TP63) expression and suppression of breast cancer cell migration." (PMID 26208975, 2015). "However, a study has been conducted in Cameroon to elucidate the involvement of SNP rs17506395 in the development of breast cancer, and it was found that the rs17506395 of the TP63 gene was not involved in the development of breast cancer (OR = 0.86, P = 0.1269)." (PMID 38585642, 2024). "Finally, based on this evidence, we hypothesized that if a metastasis suppressing IL-13-STAT6-TP63 signaling axis is activated in the absence of IL13Rα2 then STAT6 and TP63 expression levels may coordinately predict survival of patients with breast cancer." (PMID 26208975, 2015). "We further analyzed the expression data of 1762 breast cancers retrieved from GEO and found a statistically significant negative correlation of the expression between TRPS1 and TP63 (r = −0.3387, p < 0.001) and between CHD4 and TP63 (r = −0.3751, p < 0.001)." (PMID 30563971, 2018). "However, studies in regulating autophagy and apoptosis in breast cancer about TGF-β1 and TP63 have not been reported in word." (PMID 35480110, 2022).
ectodermal dysplasia (41 papers, 2012 to 2025). "Patients with TP63 mutations typically present with some combination of ectodermal dysplasia, facial clefts, and limb malformations ranging from syndactyly to ectrodactyly." (PMID 41141084, 2025). "Heterozygous variants in TP63 account for multiple autosomal dominant disorders defined by three key phenotypes: limb defects, ectodermal dysplasia, and facial clefting." (PMID 41510282, 2025). "In fact, autosomal dominant mutations in the human TP63 gene underlie a spectrum of syndromic disorders characterized by ectodermal dysplasia, including ankyloblepharon–ectodermal defects–cleft lip/palate (AEC) syndrome." (PMID 40508040, 2025). "Mutations in TP63 have been reported to cause at least six different syndromes, in which ectodermal dysplasia, cleft lip, and limb malformations appear in various combinations." (PMID 39937006, 2025). "In particular, SHFM and clefting are important features also in the TP63-associated disorders, which represent a specific subset of ectodermal dysplasia." (PMID 41562894, 2025). "There are three major phenotypes of TP63 pathogenic variants: ectodermal dysplasia, orofacial clefting, and split-hand/foot malformation." (PMID 40041233, 2022). "Conversely, the TP63 gene, being critical for the correct development of ectodermal-derived tissues, is associated with the occurrence of a subset of ectodermal dysplasia syndromes (i.e., P63-associated disorders) due to TP63 germ-line mutations." (PMID 33672023, 2021). "Heterozygous missense mutations in TP63 gene are associated to P63-related ectodermal dysplasia (ED)." (PMID 31949132, 2020). "Congenital limb malformations, ectodermal dysplasias, and facial clefts are the main characteristics of human patients with TP63 mutations such as ectodermal dysplasia and cleft lip/palate (EEC) syndrome and acro-dermato-ungual-lacrimal-tooth (ADULT) syndrome." (PMID 32414180, 2020). "Defects of Tp63‐/‐mice are characterized by ectodermal dysplasia, limb dysplasia, and orofacial deformities, which are consistent with the phenotype of patients carrying a TP63 mutation." (PMID 31050217, 2019). "For example, dominant TP63 mutations can also result in ectrodactyly, ectodermal dysplasia, and cleft lip/palate syndrome 3 (EEC3, OMIM 604292)." (PMID 29970136, 2018). "Heterozygous mutations in human TP63 are associated with a number of allelic syndromes characterized by orofacial defects, including Ectrodactyly-Ectodermal dysplasia-Cleft lip/palate and Ankyloblepharon-Ectodermal dysplasia-Clefting." (PMID 23028347, 2012). "Variants in TP63 are associated with broad spectrum of conditions related to ectodermal dysplasia." (PMID 41393291, 2025). "Pathogenic variants in the TP63 gene are linked to a spectrum of syndromes, including Ectrodactyly, Ectodermal Dysplasia, and Cleft Lip/Palate Syndrome 3 (EEC3); Ankyloblepharon-Ectodermal Defects-Clefting (AEC) Syndrome; Split-Hand/Foot Malformation 4; Orofacial Cleft 8; and others." (PMID 39409174, 2024). "The roles of TP63 were first described in the skin due to the striking epidermal phenotypes of TP63−/− mice and to the syndromes observed in patients with TP63 mutations, including ectodermal dysplasia, orofacial clefting, and limb malformations." (PMID 38165157, 2024). "More commonly, mutations in the TP63 gene result in ectodermal dysplasia and/or orofacial cleft." (PMID 37920856, 2023). "In conclusion, we identified a novel nonsense TP63 variant in a short-isoform-specific exon that may cause AEC/RHS-like ectodermal dysplasia." (PMID 35595744, 2022). "For ectodermal dysplasias caused by variants of the gene TP63 (encoding the transcription factor p63), the typical skin and corneal lesions may be amenable to cell therapy using genetically corrected autologous stem cells." (PMID 36147498, 2022).
ectodermal dysplasia (continued). "Here, we will focus on two ectodermal dysplasias that are caused by missense mutations in the TP63 gene: ectrodactyly, ectodermal dysplasia, and cleft lip/palate syndrome [EEC; OMIM #604292] and ankyloblepharon-ectodermal defects-cleft lip/palate syndrome [AEC; OMIM #106260]." (PMID 34422015, 2021). "Ankyloblepharon-ectodermal defects-cleft lip/palate (AEC) syndrome, a rare ectodermal dysplasia caused by heterozygous mutations in the C-terminus of TP63, is distinguished from other human TP63-associated disorders by the occurrence of severe skin erosions, especially those of the scalp." (PMID 31216312, 2019). "Although p63 isoforms are expressed in a range of tissues of different germ layer origins, germline mutations of TP63 have until now only been associated with ectodermal-related disorders manifested with three hallmark defects: ectodermal dysplasia, limb malformation and orofacial clefting." (PMID 29103147, 2018). "Indeed, TP63 mutations cause at least five different types of ectodermal dysplasia syndromes, a non-syndromic split-hand/foot malformation (SHFM4) and non-syndromic cleft lip; however its duplication has never been reported in a particular pathology." (PMID 25435912, 2014). "In addition, the multidrug-resistant pathogen Candida auris, being one of only four pathogens in the critical group in the WHO fungal priority pathogens list, was identified to be the causative agent of CMC in a father and daughter with TP63-associated ectodermal dysplasia (ED)." (PMID 38327523, 2024). "Furthermore, ectodermal dysplasia is present in all TP63 mutation syndromes." (PMID 33126320, 2020). "Both variants observed in TP63, occurring within the DNA-binding domain (DBD), are clinically associated with ectrodactyly, ectodermal dysplasia, and cleft lip-palate syndrome 3, EEC324." (PMID 41510282, 2025). "In humans, heterozygous TP63 mutations cause a group of overlapping autosomal dominant syndromes collectively known as TP63-related disorders, characterized by variable combinations of ectodermal dysplasia, orofacial clefting, and limb malformations." (PMID 41141084, 2025). "Ankyloblepharon-ectodermal defects-cleft lip/palate (AEC) syndrome is a rare genodermatosis within the tumor protein p63 gene (TP63)–related ectodermal dysplasia spectrum." (PMID 41143230, 2025). "Heterozygous TP63 mutations cause a spectrum of disorders including split‐hand/foot malformation 4 (SHFM4) and ectrodactyly‐ectodermal dysplasia‐cleft lip/palate syndrome 3 (EEC3)." (PMID 40964825, 2025). "The ectrodactyly‐ectodermal dysplasia‐cleft lip/palate syndrome 3 (EEC3, OMIM# 604292) is considered the prototype of TP63‐related disorders and is defined by the triad of ectrodactyly, ectodermal dysplasia, and cleft lip/palate." (PMID 40964825, 2025). "The combination of ectrodactyly, ectodermal dysplasia features, cleft lip and palate, and renal anomalies illustrates the broad phenotypic spectrum of TP63-related disorders." (PMID 41141084, 2025). "TP63-related disorders include various combinations of limb anomalies, ectodermal dysplasias, and orofacial clefts." (PMID 35595744, 2022). "Ankyloblepharon-ectodermal defect–cleft lip/palate syndrome and Rapp–Hodgkin syndrome are well-known TP63-related autosomal-dominant genetic disorders with various similar ectodermal dysplasias." (PMID 35595744, 2022). "Mutations in the TP63 gene cause several syndromic disorders, including ankyloblepharon–ectodermal defects–cleft lip/palate (AEC) syndrome, characterized by severe skin erosions, cleft palate, and ectodermal dysplasia." (PMID 40508040, 2025). "In case 6 (fetal cleft lip and palate, right kidney cystic hypoplasia, bilateral foot fissure, lateral toe, and abnormal hand development), the fetus carried a mutation in the TP63 gene, which was correlated to ectrodactyly, ectoderm dysplasia, and cleft lip/palate syndrome-3 (EEC3)." (PMID 31299979, 2019).
ectodermal dysplasia (continued). "EEC (ectrodactyly, ectodermal dysplasia, clefting; OMIM 604292) is an autosomal dominant developmental disorder resulting mainly from pathogenic mutations of the DNA-binding domain (DBD) of the TP63 gene." (PMID 22574117, 2012). "When the patient was 1-year-old, he was diagnosed with ectrodactyly ectodermal dysplasia-cleft lip/palate (EEC) syndrome (OMIM#604292), a TP63-related disorder without limb malformations, based on his cleft lip and palate and ectodermal dysplasia." (PMID 35595744, 2022). "In a disease case where the complete TP63 gene was lost in a larger genomic deletion region, the patient did not present any ectoderm dysplasia phenotype." (PMID 29103147, 2018).
bladder cancer (33 papers, 2011 to 2026). "In bladder cancer, loss of TP63 expression is associated with cancer progression, which highlights the contrasting roles of p63 and/or its specific isoforms in different contexts and tissues." (PMID 39791744, 2025). "In order to prioritize the 21 bladder cancer-associated SNPs within the TP63 region, we used publicly available regulatory data." (PMID 29956121, 2018). "In conclusion, we identified an enhancer region within the TP63/LEPREL1 intergenic locus containing bladder cancer risk SNPs that regulate gene expression levels in cis and, subsequently, tumor cell viability." (PMID 29956121, 2018). "Genome-wide association studies (GWAS) have led to the identification of a bladder cancer susceptibility variant (rs710521) in a non-coding intergenic region between the TP63 and LEPREL1 genes on chromosome 3q28, suggesting a role in the transcriptional regulation of these genes." (PMID 29956121, 2018). "We have also shown that TRIM29 is enriched in basal bladder cancer subtypes and is part of a TP63-regulated program that promotes migration and invasive progression." (PMID 42239777, 2026). "Similarly, another study using patient samples observed a significant loss of TP63 expression with more aggressive bladder cancers and also found an increase in Ki67 expression, a proliferation marker, suggesting that low TP63 expression is needed for bladder cancer progression." (PMID 39791744, 2025). "The authors found that the TAp63 isoform of the TP63 gene correlated with worse survival, especially in the basal bladder cancer subtype." (PMID 39791744, 2025). "It is reported that TP63 can predict the progression and survival of bladder cancer, kidney cancer, low-grade glioma, and skin cancer." (PMID 35480110, 2022). "High and low MAPK9 expression is also involved in multiple cancer pathways, such as colorectal and bladder cancers.High and low TP63 expression is involved in various diseases such as Parkinson’s disease and pancreatic cancer." (PMID 34168974, 2021). "The TF TP63 was highly expressed and essential in cell lines derived from head and neck and bladder cancers, consistent with it being a known regulator of squamous epithelium lineage." (PMID 33073517, 2020). "In our study, we aimed at fine-mapping the original GWAS signal, rs710521, within the TP63/LEPREL1 gene locus and, subsequently, at a functional characterization of genetic variants within this locus that are associated with bladder cancer risk." (PMID 29956121, 2018). "Moreover, genes such as NAT2, TP63, GSTM1, MYC, TACC3‐FGFR3, PSCA, CLPTM1L‐TERT, APOBEC3A‐CBX6, UGT1A, and CCNE1 get mutated in bladder cancer." (PMID 40755497, 2025). "Indeed, MIR205HG expression was strongly correlated with TP63 both in bladder cancer and across all TCGA cancer types." (PMID 40461454, 2025). "We have previously shown that TRIM29, also known as ATDC, is transcriptionally regulated by TP63 in basal bladder cancers where it promotes invasive progression and metastasis, but the molecular events which promote invasion and metastasis downstream of TRIM29 remained poorly understood." (PMID 38168254, 2023).
bladder cancer (continued). "Genome-wide association studies of bladder cancer identified single-nucleotide polymorphisms (SNPs) on chromosome 8q24, upstream of the MYC oncogene, on chromosome 3q28 near the TP63 tumor suppressor gene, and in the PSCA gene to be associated with bladder cancer risk." (PMID 25234557, 2014). "In human bladder cancer cells, TFAP2A was established to be positively correlated with TP63, and it positively regulated TP63 expressions." (PMID 35494004, 2022). "The TP63, CAPG, SCD, and ZNF419 were found to be significantly upregulated in the bladder cancer tissue samples." (PMID 34386423, 2021). "Among these, TP63 attenuates EMT in prostate cells and alternatively spliced isoform ΔNp63α inhibits EMT in human bladder cancer cells." (PMID 26187636, 2015). "One such pivotal candidate TF is tumor protein p63 (p63) which directs the squamous phenotype in HNSCC, a role that also extends to other epithelial cancers such as non-small cell lung cancer and a subset of aggressive pancreatic and bladder cancers." (PMID 37492374, 2023).
lung carcinoma (23 papers, 2009 to 2025). "SNP rs13064999 lies in the intron 1 of the gene TP63 at 3q28 region, where rs4488809 and rs10937405 were reported to be associated with lung cancer predisposition." (PMID 34552866, 2021). "Many lung cancers (when mutated)-related genes were up-regulated by smoking in specific cell populations, including TP63 in BC and EGFR in intermediate cells." (PMID 32727470, 2020). "In contrast, TP63, another cell-cycle-associated protein, similarly overexpressed in NE-low tumors, was reported to be a tumor suppressor associated with a better prognosis in lung cancer." (PMID 34200100, 2021). "This research also indicated genes other than TP63 that were co-downregulated with SNAI2 in several online Oncomine Lung Cancer datasets." (PMID 35201505, 2022). "So far, GWAS have identified some important lung cancer susceptibility loci: 22q12 (MTMR3-HORMAD2), 3q28 (TP63) and 5p15 (TERT-CLPM1L)." (PMID 28903315, 2017). "TP63 and its isoforms are over-expressed in a wide variety of human malignancies, such as cervical, head and neck, and lung cancer." (PMID 26075610, 2015). "TP63 is an appealing target located at the tip of one of the most prevalent region of amplification in lung cancer." (PMID 19547694, 2009). "Furthermore, a comparison with the other two lung cancer subtypes revealed that, the TP63/SOX2/DMRT3 circuit was among the TFs up-regulated in a LUSC-specific manner, consistent with known properties of squamous lineage survival TFs." (PMID 29866045, 2018). "Our results indicate that specific cytogenetic alterations present in preinvasive lung lesions such as amplification or over-representation of the TP63 and MYC genes are highly associated with the diagnosis of lung cancer and therefore suggest a role of those markers in assessing lung cancer risk." (PMID 19547694, 2009). "We selected six DNA targets commonly amplified in lung cancer including two centromeric probes (CEP3 and CEP6) and four probes to areas of frequent genomic amplification, i.e. 3q28 (TP63), 5p15.2 (D523 and D5S721 markers), 8q24 (MYC), and 7p12 (EGFR)." (PMID 19547694, 2009). "TP63 activity has been shown to promote nuclear YAP activity in head and neck squamous cell carcinoma cells, but interestingly YAP has been suggested to repress the ΔNp63 expression in breast and lung cancer cell lines." (PMID 37150829, 2023). "Furthermore, IPA upstream analysis predicted the activation or inhibition state of many important transcription factors that were previously reported to be involved in the pathogenesis of lung cancer such as FOXM1, NRF2, TP63, NKX2-1, and ATF3 18,36–39." (PMID 31444368, 2019). "Here, we tested whether genomic gains in six specific loci, TP63 on 3q28, EGFR on 7p12, MYC on 8q24, 5p15.2, and centromeric regions for chromosomes 3 (CEP3) and 6 (CEP6), may provide further value in the prediction of lung cancer." (PMID 19547694, 2009).